RPL5 (ribosomal protein L5)
Description:
Component of the ribosome, a large ribonucleoprotein complex responsible for the synthesis of proteins in the cell. The small ribosomal subunit (SSU) binds messenger RNAs (mRNAs) and translates the encoded message by selecting cognate aminoacyl-transfer RNA (tRNA) molecules. The large subunit (LSU) contains the ribosomal catalytic site termed the peptidyl transferase center (PTC), which catalyzes the formation of peptide bonds, thereby polymerizing the amino acids delivered by tRNAs into a polypeptide chain. The nascent polypeptides leave the ribosome through a tunnel in the LSU and interact with protein factors that function in enzymatic processing, targeting, and the membrane insertion of nascent chains at the exit of the ribosomal tunnel. As part of the 5S RNP/5S ribonucleoprotein particle it is an essential component of the LSU, required for its formation and the maturation of rRNAs.
Synonyms: MSTP030; L5; PPP1R135; uL18
Tractability: Small molecule: an approved drug acts on it; a structure with a bound ligand is known; a high-quality ligand is known. PROTAC: UniProt records ubiquitination sites on it; ubiquitination databases record sites on it; its protein half-life has been measured; a small molecule that binds it is known. Other modalities: a drug acting on it is in phase 2 or 3 trials.
Target class: Other cytosolic protein
Gene: Protein-coding gene on chromosome 1 (92,831,990 to 92,841,924, forward strand). Ensembl gene ENSG00000122406.
Subcellular location: Cytoplasm; Nucleus, nucleolus
Subcellular location (Human Protein Atlas): Cytosol; Endoplasmic reticulum; Nucleoli; Nucleoli rim
Pathways (Reactome):
Metabolism of proteins: Eukaryotic Translation Termination; Formation of a pool of free 40S subunits; GTP hydrolysis and joining of the 60S ribosomal subunit; L13a-mediated translational silencing of Ceruloplasmin expression; PELO:HBS1L and ABCE1 dissociate a ribosome on a non-stop mRNA; Peptide chain elongation; Ribosome Quality Control (RQC) complex extracts and degrades nascent peptide; SRP-dependent cotranslational protein targeting to membrane; ZNF598 and the Ribosome-associated Quality Trigger (RQT) complex dissociate a ribosome stalled on a no-go mRNA
Metabolism of RNA: Major pathway of rRNA processing in the nucleolus and cytosol; Nonsense Mediated Decay (NMD) enhanced by the Exon Junction Complex (EJC); Nonsense Mediated Decay (NMD) independent of the Exon Junction Complex (EJC)
Cellular responses to stimuli: Response of EIF2AK4 (GCN2) to amino acid deficiency
Developmental Biology: Regulation of expression of SLITs and ROBOs
Disease: Viral mRNA Translation
Metabolism: Selenocysteine synthesis
Gene Ontology:
Molecular function: 5S rRNA binding; mRNA 3'-UTR binding; mRNA 5'-UTR binding; protein binding; RNA binding; structural constituent of ribosome; ubiquitin ligase inhibitor activity; ubiquitin protein ligase binding
Biological process: negative regulation of ubiquitin-dependent protein catabolic process; positive regulation of translation; ribosomal large subunit assembly; ribosomal large subunit biogenesis; rRNA processing; cytoplasmic translation; negative regulation of myoblast fusion; spermatogenesis; striated muscle contraction; translation
Cellular component: cytoplasm; cytosol; cytosolic large ribosomal subunit; cytosolic ribosome; endoplasmic reticulum; extracellular exosome; focal adhesion; membrane; nucleolus; nucleoplasm; nucleus; protein-containing complex; ribonucleoprotein complex; ribosome
Genetic constraint (gnomAD): Loss-of-function variants: 0 observed, 31.18 expected, observed/expected ratio (o/e) 0, 90% interval 0 to 0.096. The upper end of that interval is the gene's LOEUF score, 0.096, which puts it in group 1 of 6, group 1 being the genes least tolerant of losing a copy. Missense variants: 227 observed, 358.57 expected, observed/expected ratio (o/e) 0.63, 90% interval 0.57 to 0.71. Synonymous variants: 108 observed, 119.62 expected, observed/expected ratio (o/e) 0.9, 90% interval 0.77 to 1.06.
Gene-disease validity (ClinGen):
ClinGen rates the evidence that RPL5 causes each of these diseases.
Diamond-Blackfan anemia 6 (autosomal dominant): Definitive.
Cancer hallmarks: proliferative signalling (promotes); suppression of growth (promotes); escaping programmed cell death (suppresses); escaping programmed cell death (promotes); tumour promoting inflammation
Homologues: Orthologues: macaque RPL5 (100% identical), chimpanzee RPL5 (99% identical), rabbit RPL5 (99% identical), guinea pig RPL5 (99% identical), rat Rpl5l1 (99% identical), mouse Rpl5 (98% identical), tropical clawed frog rpl5 (92% identical), zebrafish rpl5b (87% identical), zebrafish rpl5a (85% identical), Drosophila melanogaster RpL5 (67% identical), Caenorhabditis elegans rpl-5 (58% identical).
Diseases named in the same sentence as RPL5 in open-access papers:
RPL5 is named in the same sentence as 83 diseases in open-access papers, as found by Europe PMC text mining. Sharing a sentence is not in itself a finding about the gene and the disease. The quoted sentences say what the papers report.
breast carcinoma (29 papers, 2016 to 2025). "In this study, we aimed to explore the potential role of RPL5 in breast cancer and its underlying mechanisms." (PMID 35293275, 2022). "In this study, we investigated the potential role of RPL5 in breast cancer and underlying mechanisms." (PMID 35293275, 2022). "In this study, TCGA data revealed that RPL11 and RPL5 expression was significantly lower in breast cancer tissues, and their expression levels were associated with overall survival." (PMID 32483207, 2020). "mechanism underlying RPL5-uL18 inactivation–mediated cancer commitment in breast cancer and glioblastoma." (PMID 30650663, 2019). "uL18/RPL5 downregulation is also associated with breast cancer cell proliferation and tumor progression in transgenic mice and human tumor xenograft mouse model." (PMID 29674660, 2018). "RPL5 was located at a significant peak of heterozygous deletion or mutated in 11% of glioblastoma, 28% of melanoma and 34% of breast cancer samples." (PMID 28147343, 2017). "RPL5 down-regulation in breast cancer is also associated with a poor prognosis." (PMID 34873618, 2021). "In addition, RPL5 has been shown to be involved in suppression of MYC expression and RPL5 knockdown is associated with increased MYC expression in breast cancer cell lines." (PMID 30546832, 2018). "Recently, it has been reported that RPL5 inhibits breast cancer cell growth by regulating ER stress and autophagy through E2F1 in breast cancer cells and tissues." (PMID 39684863, 2024). "The present study showed that RPL5 is downregulated in breast cancer, whereas its overexpression inhibits tumor cell growth." (PMID 35293275, 2022). "Taken together, RPL5 inhibited the growth of breast cancer cells by modulating ERS and autophagy via the regulation of E2F1." (PMID 35293275, 2022). "As far as we know, previous studies on RPL5 in melanoma, liver cancer, breast cancer and non-small cell lung cancer have mentioned that RPL5 plays an important role in its occurrence and development, but none of them have been studied in depth." (PMID 36384455, 2022). "RPL5 is involved in the development and progression of a variety of tumors, such as melanoma, liver cancer, breast cancer, and non-small cell lung cancer." (PMID 36384455, 2022). "It was found that both RPL11 and RPL5 expression levels were significantly lower in breast cancer tissues (n = 1099) than in normal breast tissues (n = 113)." (PMID 32483207, 2020). "To further explore the biological effect of RPL11 and RPL5 in breast cancer, we analyzed their expression using TCGA data." (PMID 32483207, 2020). "These include acute lymphoblastic T-cell leukemia (T-ALL) (RPL10 and RPL5); glioma, melanoma, and breast cancer (RPL5); colorectal and endometrial cancer (RPL22); and chronic lymphocytic leukemia (RPS15)." (PMID 31799629, 2020). "Our results indicated that overexpression of RPL11 or RPL5 suppressed breast cancer cell proliferation, blocked G1–S cell-cycle transition, and induced cancer cell apoptosis." (PMID 32483207, 2020). "In contrast, silencing of RPL5 in breast cancer cells promoted cell cycle progression and accelerated tumor progression in a xenograft mouse model." (PMID 30425236, 2018). "We experimentally validated the role of RPL5 as haploinsufficient tumor suppressor in breast cancer cell and mouse models." (PMID 28147343, 2017).
breast carcinoma (continued). "In conclusion, RPL5 heterozygous inactivation occurs at high incidence (11-34%) in multiple tumor types, currently representing the most common somatic ribosomal protein defect in cancer, and we demonstrate a tumor suppressor role for RPL5 in breast cancer." (PMID 28147343, 2017). "c-MYC protein was upregulated in both breast cancer cell lines with RPL5 knockdown in vitro and in MDA-MB-231 tumors in vivo but downregulated in MCF7 tumors." (PMID 28147343, 2017). "In both subcutaneous breast cancer models, RPL5 knockdown significantly increased the tumor weight when sacrificing the animals (MCF7 p = 0.009 and MDA-MB-231 p = 0.044)." (PMID 28147343, 2017). "Among them, RPL5 was the strongest candidate affected in 11-34% of glioblastoma, melanoma and breast cancer patients." (PMID 28147343, 2017). "RPL5 knockdown in breast cancer cell lines enhanced G2/M cell cycle progression and accelerated tumor progression in a xenograft mouse model." (PMID 28147343, 2017). "A high RPL5 predicts a good prognosis for patients with breast cancer." (PMID 35293275, 2022). "This study aimed to determine the role of RPL5/E2F transcription factor 1 (E2F1) in breast cancer." (PMID 35293275, 2022). "RPL5 acts as a tumor suppressor in glioblastoma, melanoma, and breast cancer." (PMID 35293275, 2022). "In the present study, we explored the role of RPL5 in breast cancer." (PMID 35293275, 2022). "In breast cancer, downregulation of RPL5 accelerates the development of tumors and leads to poor prognosis; however, the effects of RPL5 on ERS in breast cancer remain unknown." (PMID 35293275, 2022). "It was found that RPL5 was downregulated in breast cancer cells and tissues." (PMID 35293275, 2022). "In this study, the overexpression of RPL5 induced ERS in breast cancer cells." (PMID 35293275, 2022). "In this study, the expression of RPL5 was significantly decreased in breast cancer tissues." (PMID 35293275, 2022). "We hypothesized that RPL5 regulated the progression of breast cancer via regulating ERS and autophagy." (PMID 35293275, 2022). "Knockdown of RPL5 in breast cancer cell lines promotes G2/M cell cycle progression and enhances tumor growth in xenograft mouse model which confirms the potential suppressive role of RPL5 in breast cancer." (PMID 34873618, 2021). "A recent study carried out by Fancello and colleagues has found that, in approximately 34% of invasive breast cancer samples, ribosomal alterations were driven by mutations in the uL18/RPL5 ribosomal protein genes, thus highlighting the suppressor role of RPL5 in breast cancer." (PMID 33194751, 2020). "RPL5 has been reported to be a tumor suppressor gene in breast cancer development." (PMID 31874600, 2019). "Evidence to date suggests that RPL5 (along with numerous other ribosomal protein genes [RPGs]) is a haploinsufficient tumor suppressor gene which is frequently deleted in a range of cancers including glioblastoma multiforme, melanoma and breast cancer." (PMID 30546832, 2018). "Importantly, 50% reduction of RPL5 levels in breast cancer cell lines increased cell proliferation and tumor progression in mouse xenograft models, further supporting a haploinsufficient tumor suppressor role for RPL5 in human cancer." (PMID 28147343, 2017). "Moreover, patients with low RPL5 expression displayed worse overall survival in glioblastoma and in one breast cancer cohort." (PMID 28147343, 2017). "We chose for breast cancer models, because of the high incidence of RPL5 inactivation in BRCA." (PMID 28147343, 2017).
breast carcinoma (continued). "Four of the ten late-type genes, the ribosome-related factors EIF4B, RPL5, RPL3, and the tumor angiogenesis modifier EPN3 were significantly associated with MFS in the late period also in a meta-analysis of tamoxifen-treated breast cancer cohorts." (PMID 27926932, 2016). "This study suggests that RPL5 might be a potential target for breast cancer therapy." (PMID 35293275, 2022). "However, the potential role of ribosomal protein L5 (RPL5) on ERS in breast cancer remains unclear." (PMID 35293275, 2022). "These include relapsed and de novo T-cell acute lymphoblastic leukemia (T-ALL; RPL5, RPL22, and RPL10, respectively); gastric, endometrial and colorectal cancer (RPL22); multiple myeloma, melanoma, glioblastoma and breast cancer (RPL5) and others." (PMID 35052397, 2021). "TCGA data revealed significantly lower RPL11 and RPL5 expression in breast cancer tissues; additionally, overexpression of RPL11/RPL5 significantly suppressed breast cancer cell proliferation and G1–S cell cycle transition and induced apoptosis in vitro." (PMID 32483207, 2020). "Next, we injected the breast cancer cell lines subcutaneously into the left (ctrl vector) and right (shRPL5 vector) flanks of NSG mice to identify the role of RPL5 in breast cancer progression." (PMID 28147343, 2017). "We identify RPSA, RPS5, RPS20, RPL5, RPL11 and RPL23A as six interesting cancer driver candidates and show a tumor suppressor role for RPL5 in the context of breast cancer." (PMID 28147343, 2017).
breast carcinoma (continued). "Furthermore, E2F1 reversed the effects of RPL5 on ERS and autophagy, suggesting that RPL5/E2F1 modulates ERS and autophagy in breast cancer." (PMID 35293275, 2022). "We found that RPL5 regulated ERS and autophagy of breast cancer cells via regulating E2F1." (PMID 35293275, 2022). "Moreover, overexpression of RPL5 enhanced the P62 level and reduced the LC3-II/LC3-I ratio, suggesting that RPL5 promotes ERS and suppresses autophagy in breast cancer cells." (PMID 35293275, 2022). "RPL5 was downregulated and E2F1 was upregulated in breast cancer." (PMID 35293275, 2022). "No significant variation in RPL5 expression between breast cancer and the control plasma samples was found (p = 0.5)." (PMID 34359739, 2021). "Additionally, RPL5 downregulated E2F1, which was overexpressed in breast cancer cells." (PMID 35293275, 2022). "Three late-type genes, EIF4B, RPL5 and RPL3, were found to be significantly associated with late metastasis in two or more cohorts, all associated with longer MFS in the univariate Cox analysis, in agreement with findings in the node-negative, untreated breast cancer cohorts." (PMID 27926932, 2016).